MMP7 (matrix metallopeptidase 7)
Diseases named in the same sentence as MMP7 in open-access papers (continued):
Sharing a sentence is not in itself a finding about the gene and the disease.
tumor (continued). "Another pathway is the downregulation of MMP-7 and MMP-9, which are responsible for cancer progression and metastasis of malignant tumor cells." (PMID 33435313, 2021). "We found that the protein level of MMP2, MMP7, MMP9, MMP12, and MMP14 in the tumor tissue were basically higher than that in the normal tissue." (PMID 34804973, 2021). "We found that, the transcriptional level of MMP1, MMP3, MMP7, MMP9–MMP12, and MMP14 in tumor were significantly upregulated, both in public database and in our samples." (PMID 34804973, 2021). "In BC, numerous subtypes of MMPs containing MMP1, MMP7, MMP9 and MMP11 have investigated a positive correlation between increased levels of MMPs and tumour progression." (PMID 34142438, 2021). "In tumor bearing mice CCL24, CD163 and MMP7 were upregulated after therapy and IL24 and Odc1 were downregulated (p > 0.05)." (PMID 34944584, 2021). "We found that MMP1, MMP3, MMP7, MMP9–MMP12, and MMP14 were significantly upregulated in tumor tissue, while MMP28 was significantly downregulated in tumor tissue." (PMID 34804973, 2021). "CCL18+M1, CXCL9+M2, and TIMP1+M3 were enriched in tumor tissues and were regarded as TAMs, whereas SELENOP+M4, MMP7+M5, CHIT1+M6, and PPARG+M7 were enriched in normal tissues and considered as resident tissue macrophages (RTMs)." (PMID 34659209, 2021). "Previous studies showed that the expression levels of MMP2, MMP7 and MMP9 is positively correlated with the plasticity of tumor cells, such as invasion depth, metastasis distance, and vascular permeability." (PMID 34696818, 2021). "In the furthermore bioinformatics analysis, we found that MMP1, MMP3, MMP7, MMP9, MMP12, MMP13 all increased in the tumor as compared with the normal esophageal tissues." (PMID 34559117, 2021). "In breast and tumor tissues, delphinidin treatment also inhibits the expression of β-catenin, p-GSK-3β, c-Myc, cyclin-D1, and MMP-7 and upregulates miR-34a, a master regulator of tumor suppression." (PMID 33540611, 2021). "MMP-3 can activate other MMPs, such as MMP-1, MMP-7, and MMP-9, to promote the progression of tumor initiation." (PMID 34944846, 2021). "Only MMP2, MMP7 and MMP14 are shown to potentiate tumor growth and/or metastasis in multiple independent papers." (PMID 32325664, 2020). "Evidences also suggest that TAMs promote tumor metastasis through producing matrix metallopeptidase (MMP), such as MMP2, MMP7, and MMP9." (PMID 33201893, 2020). "The results were promising—they showed an obvious correlation between overexpression of MMP-7 and higher TNM (T-tumor, N-nodus, M-metastases) stages, higher invasive grade, and presence of lymph nodes metastasis." (PMID 32751899, 2020). "MMP-2, MMP-7, MMP-9, and MMP-12 belong to metalloproteinases (MMPs), a family of zinc-binding enzymes related to tumor invasion and angiogenesis." (PMID 33113766, 2020). "For example, the upregulated CLEC3A has been shown highly expressed on the tumor cell surface, and the cleavage of CLEC3A by MMP7 was reported to weaken tumor cell adhesion and migration." (PMID 32539762, 2020). "AURKA overexpression was also suggested to increase the expression of MMP-2, MMP-7, MMP-9, leading to tumor metastasis by degrading extracellular matrix proteins." (PMID 33245732, 2020). "The coexpression of MMP-7 and TIMP-1 in tumour tissue reflects a high level of activation of the entire proteinase system, which indicates an increase in tumour growth and metastasis." (PMID 33005257, 2020). "In contrast, instead of suggesting SMARCA4 as a tumour suppressor gene, Kaufmann et al45 provided evidence that the over‐expression of SMARCA4 was observed to enhance cell growth and invasiveness of HCC and that it might be linked to cyclin B, cyclin E and matrix metalloproteinase 7 (MMP7)." (PMID 32162380, 2020). "Among all MMPs, MMP-1, MMP-2, MMP-3, MMP-7, and MMP-9 are involved in almost all stages of tumor growth, angiogenesis, and metastasis." (PMID 32685465, 2020).
tumor (continued). "According to another study, EGCG decreased MMP-2 expression through JNK signaling and inhibited MMP-7, MMP-9, and MMP-12 in tumor tissues." (PMID 33113766, 2020). "MMP7, which was previously shown to be expressed in human PDAC samples and affects acinar cell apoptosis, metaplasia, and tumor progression, was also detected in the human PDAC sample analyzed in this study." (PMID 32908137, 2020). "Increased blood MMP-7 and TIMP-1 levels occur when the proteins enter the circulation from tumour tissues." (PMID 33005257, 2020). "High levels of MMP-7 together with PTEN down-regulation where detected in CRC and were related to tumor stage and progression." (PMID 32410997, 2020). "It has been shown that the MMP7, LAMC2, and EGFR expressions were correlated with tumor aggressiveness, advanced T grade, and tumor stage in GC tumors." (PMID 32467737, 2020). "MMP7 is one of the target genes downstream of β-catenin/TCF signaling and plays a crucial role in promoting tumor cell migration and invasion." (PMID 31285694, 2019). "In this study, we discovered that upregulation of c-Myc promoted transactivation of GP73 in a mildly hypoxic tumor microenvironment and GP73-mediated trafficking of intracellular MMP-7, resulting in HCC metastasis." (PMID 31591387, 2019). "Their conclusion was that an elevated MMP7 and MMP9 play a role in the release of circulating tumor cells into the peripheral blood." (PMID 31191742, 2019). "Knockdown of HPSE is accompanied by downregulation of MMP1, MMP7, MMP10, and MMP13, all of which are directly involved in the degradation of extracellular matrix and facilitate tumor cell invasion." (PMID 31001480, 2019). "Increased MMP (e.g., MMP-2, MMP-7 and MMP-9) expression occurs frequently upon Wnt stimulation of tumour cell invasion." (PMID 31718047, 2019). "In summary, we found dramatic upregulation of MMP7 and FBLN5 degradative products in tumor macrophages of EOC." (PMID 29581841, 2018). "The correlation between CTHRC1 and MMP7 and MMP9 expression was further confirmed by IHC results obtained from 230 clinical NSCLC tumour samples." (PMID 29631554, 2018). "Specifically, chemerin contributed to tumor growth by inducing phosphorylation of p38 and ERK 1/2 MAPKs and upregulating IL-6, MMP-7, and VEGF." (PMID 30555465, 2018). "Consistent with the ELISA data, CTHRC1 expression was significantly correlated with MMP7 and MMP9 expression in primary tumour tissues." (PMID 29631554, 2018). "Matrix metalloproteinase-7 (MMP-7), an enzyme that can degrade the composition of extracellular matrix, is highlighted for its pivotal role in tumour progression and metastasis." (PMID 30467610, 2018). "As shown in the present study, significantly higher expression of CTHRC1, MMP-7 and MMP-9 was observed in a cohort of NSCLC sera and surgically resected tumour tissues." (PMID 29631554, 2018). "In an in vivo tumour model, it was shown that that the protein, mRNA expression and/or activity of MMP-2, MMP-3, MMP-7 and MMP-9 were significantly higher in UVB-exposed skin and tumours of IL-12 knockout mice compared with wild-type mice." (PMID 29555826, 2018). "Tumour suppression activity was validated in vitro, and the KIF3A-mediated ERK1/2/β-catenin/MMP7 signalling pathway was demonstrated to mediate the anti-tumour function, at least in part." (PMID 28423710, 2017). "Matrix metalloproteinases (MMPs) including MMP-2, MMP-7, and MMP-9 are known to promote tumor progression and cancer stemness." (PMID 29340100, 2017). "Since MMP2, MMP7 and MMP9 are important for the degradation of the tumor matrix, we investigated their protein levels by Western blot and the activity of MMPs by zymography." (PMID 28250971, 2017).
tumor (continued). "MMPs were reported to induce tumor progression in HCC including MMP-1, MMP-2, MMP-3, MMP-7, MMP-9, MMP-11 and MMP-13." (PMID 26882566, 2016). "This vascularization facilitates the metastatic process, promoting the migration/circulation of tumor cells, thanks to matrix degradation by matrix metalloproteinases (MMP2, MMP7 and MMP9), which are released by tumor cells and by TAMs as well." (PMID 27823976, 2016). "We also investigated the role of miR-326 on expression of MMP-7 and MMP-9, which all play a key role on tumor metastasis, and results indicated miR-326 inhibited the mRNA expression of MMP-7 and MMP-9 both in A549 and SPC-A-1 cells." (PMID 26840018, 2016). "Our results demonstrate that MMP-2, MMP-7, and MMP-9 expressions correlate with various morphological features of the PDAC tumor such as inflammation, necrosis, and formation of the new blood vessels." (PMID 27429508, 2016). "We also explored the efficiency of NEAT1 on MMP-7 and MMP-9 expression, which all made sense in tumor metastasis, and results demonstrated silencing NEAT1 expression suppressed MMP-7 and MMP-9 protein expression both in A549 and H1299 cells." (PMID 27351135, 2016). "Matrix metalloproteinase-7 (MMP-7), as a member of the matrix metalloproteinase (MMP) family, is known to be involved in tumor metastasis and inflammatory processes." (PMID 27147579, 2016). "CD44 mediates the recruitment of active MMP-7 and HB-EGF precursor to form a complex on the surface of tumor cells." (PMID 27271600, 2016). "Several downstream target genes of WNT/β-catenin signaling, such as CD44, C-myc, MMP2, MMP7 and TIMP2, can affect tumor growth, proliferation, invasion and metastasis." (PMID 27835587, 2016). "Genetic analysis with microarray data showed an enrichment of proneural markers as OLIG2 in the IE tumours, whereas CE tumours expressed VEGF, MMP7 and Matrix Gla proteins." (PMID 27350391, 2016). "MMP7 and MMP9 induced syndecan 1 and CXCL6 production in tumor cells, which act as chemoattractants for neutrophils and mediate their influx to the tumor microenvironment." (PMID 26956475, 2016). "Taken together, our study demonstrates that S1P induces advanced tumor phenotypes of HCC via establishing an MMP-7/syndecan-1/TGF-β1 autocrine loop, and implicates targetable S1P1-PI3K/AKT-HPSE-MMP-7 signaling axe in HCC metastasis." (PMID 27556509, 2016). "We tested possible expression changes of five genes (TACSTD, MMP7, ALDH1A3, MKI67, GLUT1) in tumors 48 h and 14 days after mTHPC and Lipidot mediated PDT compared to untreated tumor controls." (PMID 27716314, 2016). "The expressions of MMP-2, MMP-7, and MMP-9 were mainly observed in tumor cells and peritumoral stroma." (PMID 27429508, 2016). "MMP-7 and MMP-9 expressions can be induced in cancer cells, augmented by tumor-stromal cell interaction and possibly mediated by membrane-anchored and/or soluble factors." (PMID 25885552, 2015). "MMP7 produced by tumor cells cleaved to the extracellular domain of CD44, which is a participant in the creation of an anti-adhesive milieu for tumor migration." (PMID 25885552, 2015). "The immune-reactivity scores for the expression of mTOR and p-mTOR as well as for MMP2, MMP7, and MMP9 in the tumor center correlated each with its expression at the invasive front (p < 0.001)." (PMID 26652716, 2015). "The most encouraging findings of our study is that metformin treatment led to decreased expression of several genes involved in tumor invasion and migration, including DCN, MMP7, FN1, and WFDC." (PMID 25909163, 2015). "In this study, we analyzed the tumor metastasis related factors KAI1/CD82, CD44, MMP7 and β-catenin, to provide a new direction for investigating the metastasis and prognosis of CRC." (PMID 26408312, 2015).
tumor (continued). "Due to this action, MMP-7 is involved in the degradation of extracellular matrix (ECM), adaptation of tumour microenvironment and thereby promoting the process of invasion and metastasis." (PMID 25596746, 2015). "Significantly, c-kit strongly promoted tumor cell invasiveness by increasing ETV4, which induced MMP7 expression and epithelial-mesenchymal transition (EMT) via ERK pathway." (PMID 26356816, 2015). "IHC staining reaction of the tumor was present in 44-60 % for MMP2, MMP7, and MMP9, as well as in 96 % and 80 % for mTOR and p-mTOR, respectively." (PMID 26652716, 2015). "Conversely, the tumor markers MMP7 and OPN were only expressed in tumor 1 (colon) and tumors 1 (colon) and 3 (rectum), respectively." (PMID 26517682, 2015). "In line with reduced tumor growth, expression of p-ERK, nuclear β-catenin, c-Myc and MMP-7 was found to be substantially decreased in fibulin-5-expressing H1299 tumors, compared to the parental H1299 tumors lacking fibulin-5 expression." (PMID 25909283, 2015). "Among all MMPs that are highly expressed in the tumor-bone microenvironment (MMP-2, -3, -7, -9, and -13), only osteoclast-derived MMP-7 significantly contributed to human breast-to-bone metastatic tumor growth and tumor-induced osteolysis in experimental mice." (PMID 24978435, 2014). "By associating and deacetylating Smad4, SIRT1 enzyme can influence MMP7 expression, MMP enzyme activity, and consequently, cell migration, invasion, and tumor metastasis in OSCCs." (PMID 25424420, 2014). "Taken together, these results suggest that MMP-2 and MMP-7 are involved in and essential for ATF4-mediated tumor invasion and metastasis." (PMID 25078779, 2014). "Among all of the tumor samples that were analyzed, tumors from the TE-1LM-ATF4 and TE-1HM-SCR cell groups showed strong and moderate MMP-2 and MMP-7 staining." (PMID 25078779, 2014). "It is generated through proteolytic cleavage of circulating plasminogen by a series of enzymes from the tumor environment, including the MMPssuch as MMP-2, MMP-7, MMP-9, and MMP-12." (PMID 25549350, 2014). "Examining data from TNBC / Basal subtype (from human tumor samples; GSE25055) with high MMP7 expression and low PTEN expression we found a correlation coefficient of -0.54." (PMID 24143235, 2013). "Angiostatin produced from plasminogen by MMP7 and MMP9 has been shown to have biological activities such as inhibition of endothelial cell proliferation, angiogenesis, tumor growth and metastasis." (PMID 24216994, 2013). "CD204(+) macrophages reportedly exhibit a tumor-promoting function in several tumors by secreting matrix metalloproteinase (MMP)-1, MMP-3, MMP-7, MMP-9, MMP-12, vascular endothelial growth factor (VEGF), and transforming growth factor (TGF)-β." (PMID 24376714, 2013). "Both H. pylori-exposed gastric epithelial cells and the tumor biopsies demonstrated significant up-regulation of five common genes (IL-8, CLDN1, KRT17, CLDN7 and MMP7) and down-regulation of four common genes (GPER, KIAA1324, ADA and SLC9A2)." (PMID 24321518, 2013). "MiR-126&126* play their tumor suppression function through the direct inhibition of ADAM9 and MMP7, in turn impairing the activation of their common target heparin-binding EGF-like growth factor (HB-EGF)." (PMID 23437250, 2013). "PPARγ downregulates matrix metalloproteinase-7 (MMP-7) and induces MMP inhibitors expression, suppressing tumor cell invasion." (PMID 22848209, 2012). "These two genes, together with MMP-7, MMP-9, bFGF, IL-1β and IgT7αα are closely related to tumor progression (angiogenesis, invasion and metastasis)." (PMID 21991388, 2011). "YW210.09 antibody also inhibits endogenous Wnt1 signaling in cultured tumor cells grown from MMTV-Wnt1 tumors, as observed by reduced expression of Wnt target genes Axin2 and Mmp7 to a similar extent as Fzd8CRD-Fc protein treatment." (PMID 20856934, 2010). "In contrast, MMP-7 and MMP-27 mRNA showed a weaker expression in tumor samples compared to healthy tissue." (PMID 19531263, 2009).
tumor (continued). "A total of 31 genes met these criteria and, among these, two of the most differentially expressed, CD133 and MMP7, were selected for evaluation in an independent series of BRCA1 tumours." (PMID 19826428, 2009). "The optimal transcript combination that separated tumour from normal was SLC5A8 and MMP-7 resulting in a leave-one-out error estimate of 0.128." (PMID 19689820, 2009). "The mRNA expression of MMP7, which can degrade various ECM proteins and support the role in tumor invasion and spread in HCC, has significant correlation to HIF-1α mRNA expression in our study (r = 0.593)." (PMID 19948069, 2009). "The expression of MMP-9 or TIMP-2 by tumour cells, MMP-1, 7, 9, 11, 13, or TIMP-3 by fibroblastic cells, and MMP-7, 9, 11, 13, 14, TIMP-1, or TIMP-2 by mononuclear inflammatory cells, was also significantly associated with a higher rate of distant metastases." (PMID 17342087, 2007). "Using quantitative RT–PCR, overexpression of MMP1, MMP3, MMP7, MMP11, MMP12 and MMP13 in desmoid tumours was demonstrated." (PMID 15054469, 2004). "Coexpression of MMP-7 and MMP-9 was significantly correlated with deep tumour invasion in MM and SM (P=0.008), and positive nodal metastasis (P=0.008)." (PMID 14647147, 2003). "Following treatment with RLN2-secreting CAR-T cells, type IV collagen expression in the tumor was significantly reduced by RLN2-induced MMP-9 and MMP-7 expression, potentially facilitating easier contact between the extravasated CAR-T and cancer cells after traversing the interstitial stroma." (PMID 40666525, 2025). "Mmp7 and Ifitm3 are known to promote metastasis in human CRC, and Ccl9 expression by epithelial cells promotes tumor invasion through recruitment of Ccr1+ myeloid cells to the tumor’s invasive front in a mouse model of CRC." (PMID 41384492, 2025). "The AUC for MMP-7 was also higher for CA125 (0.5428; 0.6831) and increased with tumor stages." (PMID 40332487, 2025). "The observed reduction in MMP-7 and MMP-9 mRNA levels suggests that Ht2 may modulate the ECM remodeling, potentially impairing tumor cell invasion and metastasis." (PMID 40282199, 2025). "Fibroblasts and tumor cells can secrete MMP-13, MMP-7, and MMP-14." (PMID 39247608, 2024). "MMP-7 mRNA expression was higher in tumor tissues with elevated levels of HSP47 than in non-cancerous tissues." (PMID 38907287, 2024). "MMP7 was predominantly expressed in tumour cells rather than normal epithelial cells and immune/stromal cells, consistent with the analysis in single‐cell analysis." (PMID 39187937, 2024). "Notably, HCC patients with high CSC levels exhibited an accumulation of SPP1+ macrophages (Macro_SPP1) expressing metalloproteinases (MMP9, MMP12, and MMP7) regulated by HIF1A, suggesting a hypoxic tumor region connecting Macro_SPP1 and CSC." (PMID 38521868, 2024). "MMP-13 promotes tumour angiogenesis 16, MMP-7 degrades HB-EGF and E-cadherin in the basement membrane 17, 18, and MMP-14 degrades CD-44 and electron-cadherin in the basement membrane 19, which together play a vital role in tumour invasion." (PMID 38911387, 2024). "Furthermore, FXR has a tumor suppressor effect on CRC via interacting with β-catenin and inhibiting the transcription of MMP7." (PMID 39234549, 2024). "In addition, PSMA also plays a role in the degradation of the extracellular matrix (ECM) by regulating matrix metalloproteinases, such as MMP7 and MMP9, increasing ECM breakdown and promoting tumor invasion." (PMID 39272896, 2024). "In contrast to other macrophages, TAMs have specific receptors and ligands; for example, TAM can enhance phagocytosis by binding to extracellular matrix metalloproteinase ligands (e.g., MMP-2, MMP-7, MMP-9, and MMP-12), which in turn promotes tumor growth and metastasis." (PMID 38806553, 2024). "Fibroblasts and tumour cells secrete MMP-13, MMP-7, and MMP-14." (PMID 38911387, 2024). "MMP7 and SPP1 levels were also higher in both CDKN2A+ tumor regions and nearby CDKN2A+ regions." (PMID 38888512, 2024).